TDRD15 (tudor domain containing 15)
Tractability: No criterion of Open Targets' tractability assessment is met for any kind of drug.
Gene: Protein-coding gene on chromosome 2 (21,123,968 to 21,144,368, forward strand). Ensembl gene ENSG00000218819.
Homologues: Orthologues: chimpanzee TDRD15 (99% identical), macaque TDRD15 (95% identical), rabbit TDRD15 (78% identical), dog TDRD15 (78% identical), rat Tdrd15 (57% identical), tropical clawed frog tdrd15 (36% identical), zebrafish tdrd15 (26% identical), Drosophila melanogaster tud (16% identical). Paralogues in human: TDRD6 (24% identical), TDRD1 (11% identical), TDRD7 (9% identical), TDRD5 (7% identical), TDRKH (5% identical), TDRD10 (3% identical).
Diseases named in the same sentence as TDRD15 in open-access papers:
TDRD15 is named in the same sentence as 4 diseases in open-access papers, as found by Europe PMC text mining. Sharing a sentence is not in itself a finding about the gene and the disease. The quoted sentences say what the papers report.
atopic dermatitis (1 paper, 2025). "TDRD15 was found to be significantly upregulated in the skin of patients with atopic dermatitis (AD) in comparison with the proteomic outcomes of normal hair follicles in patients with atopic dermatitis." (PMID 41487473, 2025).
TDRD15 also shares sentences with these, for which no sentence is quoted: inflammation (1 paper); inflammatory skin disease (1); tumours (1).